CYRIA (CYFIP related Rac1 interactor A)
Description:
May negatively regulate RAC1 signaling and RAC1-driven cytoskeletal remodeling (Probable). May regulate chemotaxis, cell migration and epithelial polarization by controlling the polarity, plasticity, duration and extent of protrusions (Probable).
Synonyms: FAM49A; DKFZP566A1524; FLJ11080; CYRI-A
Tractability: PROTAC: ubiquitination databases record sites on it.
Gene: Protein-coding gene on chromosome 2 (16,549,459 to 16,666,331, reverse strand). Ensembl gene ENSG00000197872.
Subcellular location: Membrane
Subcellular location (Human Protein Atlas): Nucleoplasm
Gene Ontology:
Molecular function: protein binding; small GTPase binding
Biological process: regulation of actin filament polymerization
Cellular component: membrane
Genetic constraint (gnomAD): Loss-of-function variants: 12 observed, 31.62 expected, observed/expected ratio (o/e) 0.38, 90% interval 0.24 to 0.62. The upper end of that interval is the gene's LOEUF score, 0.62, which puts it in group 2 of 6, group 1 being the genes least tolerant of losing a copy. Missense variants: 204 observed, 338.49 expected, observed/expected ratio (o/e) 0.6, 90% interval 0.54 to 0.68. Synonymous variants: 99 observed, 117.81 expected, observed/expected ratio (o/e) 0.84, 90% interval 0.71 to 0.99.
Homologues: Orthologues: chimpanzee CYRIA (100% identical), macaque CYRIA (100% identical), mouse Cyria (99% identical), rat Cyria (99% identical), dog CYRIA (98% identical), tropical clawed frog cyria (93% identical), rabbit CYRIA (91% identical), pig CYRIA (90% identical), zebrafish fam49a (84% identical), Drosophila melanogaster CG32066 (53% identical), Caenorhabditis elegans R07G3.8 (37% identical). Paralogues in human: CYRIB (80% identical).
Diseases named in the same sentence as CYRIA in open-access papers:
CYRIA is named in the same sentence as 7 diseases in open-access papers, as found by Europe PMC text mining. Sharing a sentence is not in itself a finding about the gene and the disease.
CYRIA shares sentences with these, for which no sentence is quoted: autism spectrum disorder (1 paper); cancer (1); epilepsy (1); neuroblastoma (1); pancreatic cancer (1); sarcoma (1); tumours (1).